ADAM17 (ADAM metallopeptidase domain 17)
Diseases named in the same sentence as ADAM17 in open-access papers (continued):
Sharing a sentence is not in itself a finding about the gene and the disease.
breast carcinoma (continued). "The first GeneRIF is for PubMed ID 17438092 which is an article published at Clinical Cancer Research in 2007, titled “ADAM-17 expression in breast cancer correlates with variables of tumor progression”." (PMID 23251346, 2012). "There is one GeneRIF entry showing the evidences that the gene ADAM17 is “primary breast cancer” related." (PMID 23251346, 2012). "Targeting ADAM17 with siRNA reverted the malignant phenotype in T4-2 breast cancer cell line and strongly inhibited the growth of two independent human renal carcinoma cell lines in immunocompromised mice." (PMID 23251384, 2012). "As with ADAM17 in breast cancer, the prognostic impact of ADAM9 in prostate cancer was independent of the conventionally used factors for this malignancy such as tumour size, Gleason grade and preoperative PSA level." (PMID 21906355, 2011). "● Inhibition of ADAM17 activity or downregulation of its expression decreased growth of breast cancer cells in vitro and reversed their morphological appearance to that approximating normal cells." (PMID 21906355, 2011). "As well as ADAM17 protein, high expression of ADAM17 mRNA was also found to predict adverse outcome in patients with breast cancer." (PMID 21906355, 2011). "ADAM17 is involved in the process of breast cancer development and progression, shedding ligands such as TGF-α, AREG, EGFR ligands, and betacellulin and then activating EGFR which promotes breast cancer cell growth and invasion through the PI3K/AKT and Ras/MAPK signaling pathways." (PMID 41050403, 2025). "They speculated that ADAM10 and/or ADAM17 may be involved in regulating the PD-L1/PD-1 pathway and play an important role in antitumour immunity in breast cancer." (PMID 38069391, 2023). "Moreover, a previous study in breast cancer model reported that ADAM17 was upregulated by severe hypoxia and xenografts that had been treated with bevacizumab showed significantly higher ADAM17 mRNA levels and enzyme activity compared with control tumors." (PMID 36140519, 2022). "Interestingly, ADAM17 depletion significantly decreased tumor growth and increased mouse survival in both breast cancer cell lines." (PMID 35998057, 2022). "Due to the shedding activity, ADAM17 is closely related to the formation and development of distinct cancer types, including lung cancer, ovarian cancer, breast cancer, stomach cancer, colorectal cancer, bladder cancer, melanoma, cervical cancer, pancreatic cancer, etc." (PMID 36466812, 2022). "Our results are consistent with previous studies showing that ADAM17 silencing significantly decreased the growth of nasopharyngeal cancer cells as well as cell viability, growth, and proliferation rate of breast cancer cells and suppressed cell viability of esophageal squamous cell carcinoma." (PMID 36293469, 2022). "Considering inhibition of PROCR suppresses tumor growth from transplanted PROCR+ breast cancer cells, ADAM17 could provide a new potential therapeutic target for PROCR+ TNBCs." (PMID 34281556, 2021). "In addition, MDA-MB-231 cells and Hs578T cells (human breast cancer cell lines) were used to verify the conserved regulation of ADAM17 over PROCR expression." (PMID 34281556, 2021). "The metalloprotease ADAM17 could be a potential marker, as it is highly expressed in many solid tumors, including ovarian and breast cancer." (PMID 34771725, 2021). "Interestingly, recent studies have reported an association between upregulation of ADAM10 and ADAM17 and acquired resistance to trastuzumab and lapatinib in patients with HER2-positive breast cancer." (PMID 30458861, 2018). "Indeed, ADAM17-expressing breast cancer cell-lines MCF-7 and MDA-MB-453 degrade IFN-γ within only a few hours." (PMID 27573075, 2016). "Breast cancer cell-specific ADAM17 is known to contribute to tumor growth and progression." (PMID 27738494, 2016).
breast carcinoma (continued). "In addition, the recent development of ADAM17-selective inhibitors, which are well-tolerated in the clinical setting, suggests potential use of these inhibitors in the context of breast cancer." (PMID 27738494, 2016). "Based on the observations that leukocytes in the tumor microenvironment express ADAM17, further studies were performed to determine whether leukocytespecific ADAM17 contributes to mammary tumor initiation and growth." (PMID 27738494, 2016). "Furthermore, we demonstrate that ADAM17 is expressed on leukocytes, including macrophages, within polyoma middle T (PyMT)-derived mammary tumors." (PMID 27738494, 2016). "We have previously reported increased expression of ADAM-17 in mammary tumor-bearing mice." (PMID 24550834, 2014). "Knockdown of ADAM17 inhibits breast cancer and glioma cell proliferation and invasion." (PMID 23076445, 2013). "A previous report suggested that transient inhibition of Akt phosphorylation in trastuzumab-treated HER2+ breast cancer cells can lead to increased expression of ADAM17 and consequently increased expression of the lower-molecular-weight (40 kDa) soluble form of HRG." (PMID 24044505, 2013). "This study investigated the interrelationship of the ADAM17 gene and progression of breast cancer." (PMID 23251346, 2012). "One possible mechanism was recently identified by Gijsen and colleagues, who reported that blockade of Akt can activate ADAM17 (ADAM metallopeptidase domain 17) in erbB2-overexpressing breast cancer cells, leading to release of heregulins, which can act in an autocrine manner to activate erbB3." (PMID 21939528, 2011). "One of the best validated ADAMs for predicting patient outcome is ADAM17 in breast cancer." (PMID 21906355, 2011). "In our study, we specifically investigated whether ADAM10 and ADAM17 were responsible for constitutive shedding of GPNMB/OA in breast cancer cells, thus it is possible that ADAM17 is also capable of shedding GPNMB/OA in the context of PMA stimulation." (PMID 20711474, 2010). "Therefore, we want to find out whether ADAM17 also regulate PROCR expression in human breast cancer cells." (PMID 34281556, 2021). "This approach may be of particular interest for breast cancers that critically depend on the generation of ErbB-family growth factors via ADAM10 or ADAM17 not only in terms of cell migration and metastasis but also in terms of cell proliferation and tumor growth." (PMID 28260841, 2017). "Paclitaxel-resistant breast cancer cell lines had increased EZH2, ADAM10, ADAM17, and ICOSL expression, suggesting high sICOSL-release ability." (PMID 40708008, 2025). "ADAM17 is the main sheddase for HB-EGF, TGF-α, epiregulin, and amphiregulin [57,] and it was demonstrated to be elevated in human breast carcinomas." (PMID 38317965, 2024). "In macrophages cocultured with Adam17–/– 4T1 or E0771 breast cancer cells, we found significantly lower expression of CD163 and/or CD206 in at least 1 of 2 Adam17–/– clones, as compared with macrophages cocultured with WT cancer cells." (PMID 35998057, 2022). "In our study, we identified Adam17 as the major regulator of Procr protein level in mammary epithelial cells as well as in MDA-MB-231 and Hs578T breast cancer cells." (PMID 34281556, 2021). "High expression of ADAM17 was confirmed to be related to more secretion of TGF-α and poor prognosis in breast cancer." (PMID 34182543, 2021). "We report that a high extent of ADAM17 downregulation (∆pADAM17high) during platelet activation in patients—which may occur, among others, after their interaction with metastasizing tumor cells—correlates with certain tumor stages and the occurrence of metastases in breast cancer patients." (PMID 34208863, 2021). "The inhibitor TMI-1 blocks ADAM17, ADAM10 and other MMPs and has been shown to be effective on triple negative and HER2-overexpressing breast cancer cells." (PMID 34070094, 2021).
breast carcinoma (continued). "Two genes (DAXX, ADAM17) are involved in ovarian cancer and three genes (TNFRSF1A, TIMP4, COL1A2) are exclusive to breast cancer." (PMID 31205821, 2019). "In support of this notion, ADAM17 is overactivated or overexpressed in numerous human cancers, including NSCLC (and its major LAC subtype), colon carcinoma, breast cancer, hepatocellular carcinoma, HNSCC and gastric cancer." (PMID 31438559, 2019). "Only in a very severe case of NM, a 53-year old patient with progressive breast cancer with severe neurologic deficits and diagnosis based on CSF cytology, we were able to detect MMP-9 and TNF-RI (as ADAM17 substrate) by ELISA." (PMID 28806983, 2017). "The two best studied adamalysins, ADAM10 and ADAM17, have been shown to contribute to the acquired drug resistance of HER2-positive breast cancer in response to trastuzumab." (PMID 28442704, 2016). "ADAM17-expressing human breast cancer cell lines MCF-7 and MDA-MB-453 also degraded recombinant IFN-γ, but this was attenuated by ADAM17 inhibition." (PMID 27573075, 2016). "It proved that the ADAM17 mRNA was involved in breast carcinogenesis and progression, the high expression of ADAM17 will increase the invasiveness and spreading ability of MCF-7 breast cancer cells in vitro." (PMID 25351873, 2015). "The activation of ADAM17/TACE and the shedding of EGFR ligands have also been demonstrated after binding of TGFβ to its receptor in breast cancer cells and hepatocytes resulting in cell survival." (PMID 24212818, 2011). "We previously reported the generation and characterization of a fully human, affinity-matured anti-ADAM17 monoclonal antibody, D8P1C1, which inhibits both the proliferation of an array of cancer cell lines in vitro as well as breast cancer growth in a mouse xenograft model." (PMID 41977126, 2026). "Third, cancer cells may also produce factors that affect TNF-α and IFN-γ stability as a mechanism of resistance, such as the metalloproteinase ADAM17, which degrades IFN-γ in MCF-7 and MDA-MB-453 breast cancer cell lines." (PMID 39883638, 2025). "In liver, prostate, pancreatic, and breast cancer, NO mechanisms have been identified at cGMP-related levels These mechanisms involve a cGMP pathway that triggers ERK phosphorylation, subsequently activating TACE (ADAM17) to elevate NOTCH and EGF." (PMID 38892290, 2024). "In the breast cancer cell line MDA-MB231, only weak ADAM17 was detected." (PMID 36078095, 2022). "We next examined whether ADAM17 directly regulates the number of CD163+ cells, using orthotopic mouse mammary tumors." (PMID 35998057, 2022). "As breast cancer is a heterogeneous disease, our study cohort of only 70 breast cancer patients is unfortunately not able to adequately analyze the role of platelet-derived ADAM17 in different breast cancer subgroups." (PMID 34208863, 2021). "Here, we report that platelet-derived ADAM17 (pADAM17) is regulated upon platelet activation of breast cancer patients, but not of healthy individuals." (PMID 34208863, 2021). "Small molecules drug which was a dual inhibitor of ADAM17 and ADAM10 could suppress tumor growth and recover the sensitivity of breast cancer cells to EGFR inhibitor." (PMID 34182543, 2021). "Another ADAM17 inhibitor, INCB7839, was used to present HER2 cleavage and to treat patients with HER2-positive breast cancer in combination with trastuzumab and it is also in clinical trials to prevent CD20 cleavage in combination with rituximab for the treatment of diffuse large B-cell NHL." (PMID 30805309, 2019). "Likewise, it has been postulated that ADAM17 is the main ADAM responsible for EGFR ligand cleavage and activation of EGFR in breast cancer." (PMID 28148288, 2017). "Analysis of the kmplotter database demonstrated that increased mean expression of ADAM17 and PTGS2 was associated with a non-significant trend towards reduced relapse free survival (RFS) in all breast cancer patients." (PMID 27738494, 2016).
breast carcinoma (continued). "Furthermore, some authors have demonstrated that miR-145 targeted ADAM17 and Oct4 in kidney but also MUC1 in breast cancer cells." (PMID 24504508, 2014). "ADAM17 expression was upregulated in breast cancer compared to normal breast tissue and was highest in lymph-node metastasis." (PMID 24952873, 2014). "We have demonstrated that Amphiregulin is released from the cell surface by TACE/ADAM17 and drives EGFR pathway activation in several breast cancer cell lines suggesting that inhibiting the proteolytic production of EGFR ligands is a new mechanism by which to target EGFR signaling in cancer." (PMID 24010672, 2013). "Inhibition of ADAM17-mediated shedding reduces the growth of tumor xenografts in mice, and ADAM9 and -12 enhance tumour progression in transgenic mouse models of prostate and breast cancer." (PMID 21386996, 2011). "TNF-α converting enzyme (TACE), also known as ADAM17, cleaves the extracellular domain of TGFβRI, which is released extracellularly and results in downregulation of TGF-β receptor signaling as it was demonstrated in HaCaT keratinocytes and in breast cancer cells." (PMID 32210029, 2020). "Furthermore, ADAM17 targeting using genetic, antibody-mediated or pharmacological methods suppresses cell proliferation and tumour growth in cancer models for LAC, CRC, breast cancer, prostate cancer, pancreatic cancer and ovarian cancer." (PMID 31438559, 2019). "The recent preclinical study demonstrated that the ADAM17 inhibitor BMS566394 significantly enhanced the expression of CD16 on NK cells and more importantly, it enhanced the cytotoxic activity and IFN-γ production of treated NK cells combined with trastuzumab against breast cancer cell lines." (PMID 30805309, 2019). "Together, these studies demonstrate that ADAM17 is not a key regulator of macrophage recruitment into the tumor microenvironment, but that ADAM17 in leukocytes contributes to Cox-2 expression within mammary tumors." (PMID 27738494, 2016). "In view of our data showing the activities of both ADAM10 and ADAM17 in response to trastuzumab, we would support further studies to be done to assess the efficacy of ADAM10/17 inhibitor as a novel therapy to overcome trastuzumab resistance for HER2 positive breast cancer patients." (PMID 24952873, 2014). "Therefore, our results indicate that targeting ADAM10 and ADAM17 might enhance trastuzumab response and overcome acquired trastuzumab resistance in HER2 positive breast cancer patients." (PMID 24952873, 2014). "Since ADAM17 and ADAM10 are the two best characterized ADAM proteases responsible for HER ligand shedding, we investigated the role of ADAM10 in relation to trastuzumab treatment and resistance in HER2 positive breast cell lines, in vivo and in HER2 positive breast cancer patients." (PMID 24952873, 2014). "Based on these findings, it will be of great interest to examine whether the reported effect of PKCα on tumour cell behaviour involves its stimulatory effect on ADAM17, HB-EGF-shedding, and subsequent EGFR activation, which are all know drivers in breast cancer progression." (PMID 21386996, 2011). "Since our results of overexpression experiments for ADAM17 in MCF7 cells indicated the dose-dependency between ADAM17 expression and IFN-γ degradation, i.e., IFN-γ inactivation, our results may explain the correlation of tumor progression in breast cancer to the extent of ADAM17 expression." (PMID 27573075, 2016). "However, ADAM17 expression by leukocytes localized within mammary tumors has not been examined." (PMID 27738494, 2016). "For that evaluation, we cocultured PMA-differentiated THP-1 cells with MDA-MB-231 (MDA-231) human breast cancer cells or SW480 human colon cancer cells, treated with either negative control (NC) or ADAM17 siRNA for 48 hours, and evaluated the macrophage potential to induce cancer cell invasion." (PMID 35998057, 2022).
breast carcinoma (continued). "For example, potent non-selective inhibitors of ADAM17 and ADAM10, such as INCB3619 and INCB7839 (aderbasib), have shown promise in reducing tumour growth alone or in combination with other chemotherapeutic agents when tested in preclinical models of breast cancer and NSCLC." (PMID 31438559, 2019).
COVID-19 (73 papers, 2020 to 2025). A disease caused by infection with severe acute respiratory syndrome coronavirus 2. "Data from a study involving 306 plasma samples from COVID-19 patients demonstrated a clear association between ADAM17 activity and the severity and mortality of the disease." (PMID 40431631, 2025). "Linking high ADAM-17 activity to the risk of severe COVID-19 in humans would strengthen the potential role of ADAM-17 inhibition as a therapeutic target in COVID-19." (PMID 38892098, 2024). "In conclusion, this study indicates that severe COVID-19 is associated with increased ADAM-17 activity, with possible implications for the risk of associated mortality." (PMID 38892098, 2024). "We used data from the Massachusetts general hospital COVID-19 study (306 COVID-19 patients and 78 symptomatic controls) to investigate the association between plasma levels of 33 different ADAM-17 substrates and COVID-19 severity and mortality." (PMID 38892098, 2024). "Increased ADAM-17 activity is implicated in the progression of multiple chronic diseases, diseases that are also associated with an increased risk of severe COVID-19." (PMID 38892098, 2024). "In humans, findings indicate that high levels of ADAM-17 substrates (including ACE2) are associated with severe COVID-19." (PMID 38892098, 2024). "The present study suggests that increased ADAM-17 activity, as estimated by the ADAM-17 substrates score, is associated with increased severity of COVID-19." (PMID 38892098, 2024). "Overall, in the case of the extracellular domain of ADAM17, we identified six instrumental variables that are strongly associated with severe COVID-19." (PMID 37958866, 2023). "Nevertheless, further studies are needed to ascertain the causal effect of ADAM17 in the risk of severe COVID-19." (PMID 37958866, 2023). "Taking advantage of the large amount of data from GWAS and the MR approach, the present study provides causal evidence for ADAM17’s effects on COVID-19 severity." (PMID 37958866, 2023). "In the present study, we provide evidence for a causal effect of circulating ADAM17 (extracellular domain) on the risk of severe COVID-19." (PMID 37958866, 2023). "In conclusion, an increased genetic susceptibility to elevated levels of circulating ADAM17 (extracellular domain) is associated with a higher risk of severe COVID-19." (PMID 37958866, 2023). "The multivariable MR analysis suggested a direct causal role of circulating ADAM17 (extracellular domain) in the risk of developing critical COVID-19 (OR = 1.09; 95% CI:1.01–1.17) when accounting for body mass index." (PMID 37958866, 2023). "Alterations in ADAM17 expression affect susceptibility to viral infection and the severity of COVID-19, implying the importance of targeting ADAM17 in patients with malignant tumors infected with COVID-19." (PMID 36558177, 2022). "In this work, we detected the clinical significance of IFNAR2 (2 SNPs), SLC6A20 (1 SNP) with respect to COVID-19 susceptibility and ADAM17 (2 SNPs), TMPRSS2 (1 SNP), TYK2 (1 SNP), DPP9 (1 SNP) with respect to the severity of the disease." (PMID 36292769, 2022). "ADAM17 has been implicated in modulation of COVID-19 pathogenesis through regulation of ACE2 shedding, IL-6 signaling, and TGF-β signaling." (PMID 36494335, 2022). "Additionally, ADAM17 contributes to the development of inflammatory conditions associated with COVID-19." (PMID 39292373, 2025). "This study indicates that increased ADAM-17 activity is associated with severe COVID-19." (PMID 38892098, 2024). "In addition, an increased genetic susceptibility to elevated levels of plasma ADAM-17 (the extracellular domain) is associated with a higher risk of severe COVID-19." (PMID 38892098, 2024). "This study aims to characterize eventual causal relationships between ADAM17 and COVID-19." (PMID 37958866, 2023).